PRMT5 (protein arginine methyltransferase 5)
Diseases named in the same sentence as PRMT5 in open-access papers (continued):
Sharing a sentence is not in itself a finding about the gene and the disease.
multiple sclerosis (1 paper, 2022). A progressive autoimmune disorder affecting the central nervous system resulting in demyelination. "Secondly, no significant decrease in PRMT5 protein levels was observed upon treatment with an mTOR inhibitor in MM, whereas this was previously reported in T-cell expansion in a murine multiple sclerosis model." (PMID 35757005, 2022).
myelofibrosis (1 paper, 2022). A partial or complete replacement of the bone marrow stroma by fibrous tissue. "We are concerned about that PRMT5 plays an important role in human cancers by promoting the cell proliferation, invasion, and migration, besides, PRMT5 inhibition was efficacious ameliorate leukocyte and platelet counts, hepatosplenomegaly, and fibrosis in the MPLW515L model of myelofibrosis." (PMID 36059967, 2022).
myeloid leukemia (1 paper, 2022). A clonal proliferation of myeloid cells and their precursors in the bone marrow, peripheral blood, and spleen. "Given its involvement in many cancers, PRMT5 has become a promising target for therapeutic intervention and PRMT5 inhibitors are currently being tested in clinical trials for advanced solid tumors as well as myeloid leukemia and non-Hodgkin’s lymphoma." (PMID 35803962, 2022).
non‐alcoholic fatty liver disease (1 paper, 2023). "In light of our current findings, it will be important to consider that long‐term pharmacological inhibition of PRMT5 to treat cancer may cause severe side effects in liver, i.e. induce non‐alcoholic fatty liver disease." (PMID 36946061, 2023).
osteoarthritis (1 paper, 2020). A noninflammatory degenerative joint disease occurring chiefly in older persons, characterized by degeneration of the articular cartilage, hypertrophy of bone at the margins and changes in the synovial membrane. "In this study, the potential mechanism underlying the involvement of PRMT5 in the pathological process leading to osteoarthritis (OA) was investigated." (PMID 32887644, 2020).
ovarian tumor (1 paper, 2023). "PRMT5 inhibitors combined with chemotherapy or PARP inhibitors demonstrate synergistic suppression of cancer cell proliferation and growth in breast and ovarian tumor models, including PARP inhibitor–resistant tumors." (PMID 37861290, 2023).
prostate adenocarcinoma (1 paper, 2022). "To confirm whether testosterone interference also causes the nuclear depletion of PRMT5 in human cells, we employed androgen-sensitive human prostate adenocarcinoma LNCaP cells that can take up testosterone and express endogenous CT47." (PMID 35918318, 2022).
prostate tumor (1 paper, 2017). "Protein arginine methyltransferase 5 (PRMT5) has an oncogenic function in prostate tumor and other cancer types." (PMID 28486411, 2017).
relapsing-remitting MS (1 paper, 2021). "In addition, we also study how PRMT5 is linked to disease severity in an animal model of relapsing-remitting MS." (PMID 34168658, 2021). "Here, we evaluated the role of PRMT5 on cyclin/cdk pairs and cell cycle progression, as well as PRMT5’s link to disease severity in an animal model of relapsing-remitting MS." (PMID 34168658, 2021).
retinoblastoma (1 paper, 2025). A malignant tumor that originates in the nuclear layer of the retina. "PRMT5 plays important roles in promoting retinoblastoma (RB) development." (PMID 39826691, 2025).
seminoma (1 paper, 2008). A radiosensitive malignant germ cell tumor found in the testis (especially undescended), and extragonadal sites (anterior mediastinum and pineal gland). "We had shown, that nuclear BLIMP1 and methylated H2A and H4 are expressed in IGCNU and seminoma, yet these cells express either little or cytoplasmic PRMT5." (PMID 18992153, 2008). "Finally, we asked whether BLIMP1/PRMT5 and modification of histone H2A and H4 could be detected in TCam-2, a cell line derived from a seminoma patient." (PMID 18992153, 2008). "In IGCNU a strong nuclear signal of BLIMP1 and of H2K3me2s/H4K3me2s was detected, whereas PRMT5 signal was cytoplasmatic in IGCNU and heterogeneous in seminomas." (PMID 18992153, 2008). "PRMT5 however, is not detectable in nuclei of IGCNU, and displays only a sparse nuclear localization in seminoma cells." (PMID 18992153, 2008). "Furthermore BLIMP1/PRMT5 is expressed in IGCNU and seminoma, but downregulated in nonseminomatous GCTs." (PMID 18992153, 2008). "So we speculate that in IGCNU and seminoma, BLIMP1 recruits PRMT7 to compensate for the lack of nuclear PRMT5 to mediate H2A and H4 dimethylation." (PMID 18992153, 2008).
Sepsis (1 paper, 2026). Sepsis is defined as life-threatening organ dysfunction caused by a dysregulated host response to infection. "In summary, PRMT5 regulates sepsis-induced lung injury through a methylation-dependent JAK1/STAT3 pathway, serving as a potential target for clinical intervention." (PMID 41568710, 2026). "This study collected clinical sepsis samples and detected the mRNA expression of PRMT5." (PMID 41568710, 2026). "The results showed that PRMT5 was upregulated in sepsis patients." (PMID 41568710, 2026). "PRMT5 knockdown attenuated septic symptoms in CLP mice, manifested by increased survival, reduced sepsis scores, restored physiological parameters, and alleviated lung injury." (PMID 41568710, 2026).
serous ovarian cancer (1 paper, 2025). "Here, we identify PRMT5, the main symmetric arginine methyltransferase, as a critical driver of chemoresistance in high-grade serous ovarian cancer (HGSOC)." (PMID 40091834, 2025).
skin cancer (1 paper, 2024). "Previous research strongly suggests that PRMT5 is a tumor promoter, as it is significantly overexpressed in cancers such as colon, ovarian, kidney, lung, bladder, liver, pancreatic, breast, prostate, cervical, and skin cancers." (PMID 39255317, 2024).
skin changes (1 paper, 2024). "The gene sets encompass numerous genes previously implicated in the pathogenesis of SSc, such as Acta2, Col1a1, Col3a1, Smad3, Ctgf, Msr1, Cd4, Cd8a and Cd68, supporting the potential of anti-PRMT5 in induction of SSc-like skin changes." (PMID 38684324, 2024).
synovial sarcoma (1 paper, 2023). "SHARPIN controls the activities of NF-κΒ and PRMT5, which regulate the production of ROS and are involved in both apoptotic and nonapoptotic cell death; hence, we analyzed whether knockdown of SHARPIN inhibits the activities of NF-κΒ and PRMT5 in synovial sarcoma (Yamato) cells." (PMID 37444594, 2023).
T-cell lymphomas (1 paper, 2021). "Compared to ND tissue, all B-cell and one of two T-cell lymphomas exhibit higher protein expression of MYC and PRMT5." (PMID 33989303, 2021).
teratoma (1 paper, 2008). A non-seminomatous germ cell tumor characterized by the presence of various tissues which correspond to the different germinal layers (endoderm, mesoderm, and ectoderm). "Focal cytoplasmatic expression of BLIMP1 and PRMT5 was also observed in differentiated parts of teratoma, while chorioncarcinomas were negative for both proteins." (PMID 18992153, 2008).
testis cancers (1 paper, 2025). "Our genomic analysis indicated that among all the cancers, ovarian and testis cancers have the highest levels of PRMT5 mRNA expression, suggesting that PRMT5 is a viable therapeutic target in these cancers." (PMID 40091834, 2025).
tumor syndromes (1 paper, 2020). "In contrast, nucleic PRMT5 interacts with Menin and indirectly suppresses HH signaling in MEN1 tumor syndromes, such as pancreatic islet tumors." (PMID 32859041, 2020).
uterine disorder (1 paper, 2022). A non-neoplastic or neoplastic disorder that affects the uterine corpus or the cervix. "The human study is limited by its retrospective nature, and a larger sample size or a prospective randomized design could be used in future studies to corroborate the potential effect of PRMT5 on decidualization defects observed in many uterine disorders." (PMID 36195592, 2022).
Wilms tumor (1 paper, 2025). An embryonal neoplasm characterized by the presence of epithelial, mesenchymal, and blastema components. "CircPRMT5 (circRNA derived from Protein Arginine Methyltransferase 5 gene) affects the axis miR-7-5p/KLF4 in the rare pediatric tumor nephroblastoma." (PMID 40863723, 2025). "Specifically, inverse correlations between circ-PRMT5-miR-7-5p and between miR-7-5p-KLF4 have been observed (total of n = 45 Wilms’ tumor samples)." (PMID 40863723, 2025).
yolk sac tumor (1 paper, 2008). A non-seminomatous malignant germ cell tumor composed of primitive germ cells. "Yolk sac tumors teratomas and choriocarcinomas stained focally and cytoplasmatic for BLIMP1 and PRMT5 (not shown)." (PMID 18992153, 2008).
cancer (402 papers, 2009 to 2026). A tumor composed of atypical neoplastic, often pleomorphic cells that invade other tissues. "Inhibitors of PRMT5 have demonstrated effectiveness in treating solid and hematologic malignancies, especially likely to be more effective in cancers with splicing mutations." (PMID 39964832, 2025). "MD simulations show that these cancer mutations induce distinct structural outcomes that will likely disrupt the PRMT5:MEP50 interaction." (PMID 40919714, 2025). "PRMT5 overexpression has been reported across numerous cancer types and is often associated with reduced patient survival." (PMID 41226455, 2025). "Our findings suggest that a sustained cancer‐relevant alternative RNA splicing programme desensitises NB cells to apoptosis, and identify PRMT5 as a potential therapeutic target for high‐risk disease." (PMID 39021294, 2025). "Protein arginine methyltransferase 5 (PRMT5) is over‐expressed in a wide variety of cancers and is implicated as having a key oncogenic role, achieved in part through its control of the master transcription regulator E2F1." (PMID 39021294, 2025). "PRMT5 and its accompanying methyltransferase activity has been implicated in cancer tumorigenesis and as a marker of poor prognosis, suggesting an oncogenic role in many human cancers and making it an attractive therapeutic target for drug development." (PMID 40968252, 2025). "Accumulation of MTA in cancer cells partially blocks PRMT5, causing reduced methylation of histone tails and leading to the modification of chromatin condensation." (PMID 41465382, 2025). "MTA-cooperative PRMT5 inhibitors are designed to selectively target the PRMT5 form in MTAP-deficient cancer cells by enhancing the natural inhibitory effect of accumulated MTA, sparing normal tissues." (PMID 39826691, 2025). "Beyond its physiological functions, PRMT5 has been implicated in various pathological conditions, such as cancer and inflammatory diseases." (PMID 40790333, 2025). "Beyond its role in splicing, PRMT5’s association with maintaining stem-like properties in cancer cells reinforces the concept that elevated PRMT5 activity creates a favorable cellular environment for MCPyV-driven oncogenesis." (PMID 40846633, 2025). "We and others have also shown that KAT5 and PRMT5 mutations are endemic in human cancers, which have destabilized DSB repair machineries." (PMID 39874873, 2025). "In a recent example, the MTA-cooperative PRMT5 inhibitor, AZ-PRMT5i-1, has shown potent inhibitory effects on specific cancer cell lines, particularly those with MTAP deficiency." (PMID 39826691, 2025). "MTAP loss leads to MTA accumulation, making MTAP-deficient cancer cells susceptible to PRMT5 inhibition." (PMID 40362535, 2025). "While MTAP deletion is not sufficient to affect splicing fidelity, it renders these cancers vulnerable to further inhibition of Prmt5 activity either by genetic mutations or small molecule inhibitors." (PMID 39862967, 2025). "Inhibition of PRMT5 in MTAP-deficient cancers offers a promising strategy to exploit this synthetic lethality, potentially improving outcomes in tumors harboring this common genomic alteration." (PMID 39826691, 2025). "This creates a metabolic vulnerability in MTAP-deficient cancers, as the inhibition of PRMT5 is more sensitized than normal cells for disrupting essential methylation-dependent processes required for cell survival." (PMID 39826691, 2025). "MTAP loss, with consequent MTA accumulation, renders cancer cells more vulnerable to the further inhibition of PRMT5 and can predict sensitivity to target therapies that inhibit PRMT5 or MAT2A." (PMID 38893092, 2024). "Therapeutic inhibition of PRMT5 has been proposed as synthetically lethal in cancers with MTAP loss." (PMID 38480701, 2024). "Upregulated or highly activated PRMT5 expression has been linked to a poor prognosis in several types of cancer." (PMID 38827324, 2024).
cancer (continued). "Next-generation PRMT5 inhibitors such as MRTX1719, TNG908, and TNG462 were subsequently designed to fully inhibit PRMT5 activity in MTAP-deficient cancer cells while sparing normal cells." (PMID 39337530, 2024). "In previous work, PRMT5 knockdown was shown to suppress cell proliferation, while PRMT5 overexpression caused increased cancer cell proliferation, suggesting a role in cancer cell growth." (PMID 38760429, 2024). "The interaction between MTAP loss and codeletions in MAT2a or PRMT5 is characterized as synthetic lethal in cancers." (PMID 38000655, 2024). "More seriously, high PRMT5 expression in human cancers is implicated in tumor promotion through histone tail modifications that repress target miRNAs and is correlated with worse prognosis of patients in a number of cancer types." (PMID 39711357, 2024). "PRMT5 overexpression has been implicated in tumor development and the progression of various cancers, including breast, hepatocellular, brain, and lung." (PMID 39337530, 2024). "Our group has shown that nuclear PRMT5 is associated with differentiated cells and better prognosis, while cytoplasmic PRMT5 is linked to less differentiated, aggressive cancer cells." (PMID 39201539, 2024). "The regulation of proliferation by PRMT5 and the direct interaction of PRMT5 with proteins that are frequently dysregulated or mutated in cancer indicate that PRMT5 functions as an oncogene." (PMID 39255317, 2024). "Mutations in PRMT5 genes are rare and thus control of PRMT5 in cancer is a viable therapeutic strategy." (PMID 36819050, 2023). "PRMT5 has been shown to be overexpressed in several types of cancer and associated with a more aggressive phenotype and poorer prognosis." (PMID 37400960, 2023). "Aberrant expression and activation of PRMT5 is frequently observed in various human cancers and associated with poor prognosis and survival." (PMID 37173967, 2023). "PRMT5 loss improves sensitivity of cancer cell lines to radiation and interstrand cross-linking agents." (PMID 37861290, 2023). "The overexpression of PRMT5 is observed in various cancers and is associated with worse survival rates." (PMID 36980950, 2023). "Since RB1 loss-of-function mutations occur across various tumor types, we also examined the effect of PRMT5 silencing in other RB-deficient cancer cell lines." (PMID 37502925, 2023). "PRMT5 also regulates other pathways in the cell, and mutations and even mislocalization of this protein have been detected in cancers." (PMID 37047013, 2023). "Abnormal angiogenesis is a critical factor in tumor growth and metastasis, and protein arginine methyltransferase 5 (PRMT5), a prominent type II enzyme, is implicated in various human cancers." (PMID 37400960, 2023). "Among PRMTs, PRMT5 is believed to be highly associated with tumor formation, with PRMT5 overexpression observed in various cancers." (PMID 36980950, 2023). "PRMT5, an oncoprotein, has been implicated in various stages of human cancer progression and development by altering signaling pathways." (PMID 37400960, 2023). "In this report, we analyzed all reported PRMT5 mutations appearing in cancer cells using data from the Catalogue of Somatic Mutations in Cancers (COSMIC)." (PMID 37047013, 2023). "Studies have shown that overexpression of PRMT5 is associated with the development and progression of various types of cancer, including lung, breast, prostate and liver." (PMID 37461162, 2023). "Based on an analysis employing the Catalogue of Somatic Mutations in Cancer (COSMIC), a comprehensive collection indicates a total of 338 PRMT5 mutations across various cancer types." (PMID 38203325, 2023). "Therapeutic inhibition of PRMT5 has been proposed as synthetically lethal in cancers with loss of MTAP." (PMID 37502925, 2023).